EGLN3 (egl-9 family hypoxia inducible factor 3)
Diseases named in the same sentence as EGLN3 in open-access papers (continued):
Sharing a sentence is not in itself a finding about the gene and the disease.
tumor (continued). "This study further demonstrates USP9X’s tumor-suppressive function in CCA, mediated through EGLN3 stabilization." (PMID 41301681, 2025). "We observed a higher DNA methylation level of the HIF1A promoter region in normal tissues compared to tumors (p = 0.002) and, on the contrary, higher DNA methylation in promoter regions of EGLN2 and EGLN3 (p = 0.04 and p < 0.0001) in HNSCC tumor tissues." (PMID 38928200, 2024). "Seven genes, PFKFB4, ALDOA, EGLN3, EHHADH, GAPDH, HMGCS2, and ENO2, related to tumor FDG uptake were revealed to have a good prognostic value for survival in HCC." (PMID 35174098, 2022). "Therefore, EGLN3 may play a role as a tumor suppressor in various type of tumors." (PMID 34112167, 2021). "The first group included CA9, NDUFA4L2, EGLN3, BHLHE41, VWF, IGFBP3, and ANGPTL4, whose expression levels were coordinately decreased during tumor progression." (PMID 34046336, 2021). "Supporting the notion of activated immune suppression is the positive correlation of EGLN3-derived peptide presentation and PD1 RNA expression in the tumor tissue (p = 0.020)." (PMID 32228647, 2020). "Thus, one limitation of our study is that other model systems that better resemble the in vivo tumor situation, such as microtumors or cancer organoids, might be more appropriate to understand the function of EGLN3 in ccRCC and to assess its feasibility as a drug target." (PMID 32228647, 2020). "Using global gene expression analysis, we found that a panel of commonly observed hypoxia-inducible genes, including BNIP3L, EGLN3, LOXL4 and P4HA1, were significantly upregulated in the EGFP+ MDA-MB-231 tumor cells, compared to the EGFP− cells." (PMID 29510720, 2018). "In this study we examined the contribution of important HIF-responsive genes such as VEGF, CCND1, ANGPTL4, EGLN3, ENO2, GLUT1 and IGFBP3 to tumor growth in a xenograft model using immune-compromised nude mice." (PMID 24260413, 2013). "We found significantly higher mRNA levels of EGLN3, HIF1A, GLUT1, VEGF, and CA9 (p = 0.021; p < 0.0001; p < 0.0001; p = 0.004, and p < 0.0001, respectively) genes in tumor tissues compared to normal ones and downregulation of the EGLN1 mRNA level in tumor tissues (p = 0.0013)." (PMID 38928200, 2024). "We demonstrate for the first time that the expression of the genes CA9, NDUFA4L2, EGLN3, BHLHE41, IGFBP3, and ANGPTL4, regulated by HIF1, is largely correlated, and along with VWF, the expression levels of these genes during tumor progression decreased coordinately." (PMID 34046336, 2021). "EGLN3 overexpression induces cell apoptosis in a nerve growth factor dependent manner through caspase-3 activation and focal adhesion kinase HIF-1 phosphorylation independently, which participates in the growth and invasion of tumor cells." (PMID 34112167, 2021). "We further discovered that the lack of ANGPTL4, EGLN3 or ENO2 expression did not change tumor growth." (PMID 24260413, 2013). "Surprisingly, the shRNA construct EGLN3-692 that efficient suppressed the protein expression of EGLN3 did not reduce the tumor growth (the small increase in tumor weight after EGLN3 knockdown was not statistically significant)." (PMID 24260413, 2013). "Moreover, the protein levels of four selected genes (except EGLN3 due to a lack of data) in cervical tissue were higher in tumor samples compared to normal samples, consistent with gene expression levels according to the Human Protein Atlas database." (PMID 36551576, 2022). "So as these genes—CA9, NDUFA4L2, BHLHE41, and EGLN3—are HIF-1α-regulated, from the standpoint of the metastasis biology, a decrease in their expression might suggest a transition of tumor cells to a more malignant condition after an adaptation process that might provoke metastases." (PMID 31936274, 2020). "Next we examined whether EGLN3, one of the most highly induced HRG, plays any role in tumor growth." (PMID 24260413, 2013).
cancer (72 papers, 2007 to 2025). A tumor composed of atypical neoplastic, often pleomorphic cells that invade other tissues. "Transcriptomic analysis revealed that FAA up-regulated Egl-9 family hypoxia inducible factor 3 (Egln 3) and downregulated several cancer-associated pathways including Hippo, mTOR, and Wnt signaling." (PMID 38613073, 2024). "In numerous tumors, EGLN3 was implicated in cancer cell invasion, migration, and proliferation." (PMID 39682235, 2024). "Studies have shown that HIF1A can interact with its downstream target proteins PKM2 and PHD3 (EGLN3), ultimately playing an important role in the reprogramming of cancer cell glucose metabolism." (PMID 40721814, 2025). "Recent studies highlight that EGLN3 can shield cancer cells from death induced either by hypoxia or other apoptotic factors." (PMID 38928200, 2024). "Dysregulation of EGLN3 was observed in various cancers, however, it can act as both oncogene and suppressor in cancers." (PMID 35549979, 2022). "In this regard, our study revealed a novel cell-intrinsic mechanism for EGLN3 inactivation in regulating cancer growth." (PMID 35124697, 2022). "This work sheds new light on the role and mechanism for EGLN3 catalytic activity in regulating cancer growth." (PMID 35124697, 2022). "There is a long-standing puzzle of the relevance for hypoxic induction of EGLN3 expression in cancers." (PMID 35124697, 2022). "EGLN3 catalyzes the hydroxylation of extracellular signal-regulated kinase 3 (Erk3), a potent driver of cancers." (PMID 35124697, 2022). "So far, various functions have been proposed for EGLN3 in cancer, ranging from pro-apoptotic to growth-promoting and metabolic functions." (PMID 32228647, 2020). "To identify circRNAs with a putative function in ccRCC initiation/progression, we selected circRNAs from host genes with putative roles in angiogenesis and hypoxia in ccRCC and other cancers including EGLN3, NOX4, and RHOBTB3." (PMID 31575051, 2019). "EGLN3 is involved in the G1>S transition in carcinoma cells wherein its up-regulation is a direct response to hypoxia as a means for survival while under stress." (PMID 27682873, 2017). "Screening studies have shown differential expression of EGLN3 in cancer cells." (PMID 37443682, 2023). "Manipulating EGLN3 activity holds promise for cancer treatment." (PMID 35124697, 2022). "EGLN3 catalyzes the hydroxylation of extracellular signal-regulated kinase 3 (Erk3) and increased its stability, which is recognized as a strong, driver of cancers." (PMID 36552262, 2022). "EGLN3 arrest cancer cells in G1 phase and mediates apoptosis." (PMID 34112167, 2021). "Furthermore, EGLN3 has been shown to be upregulated in a number of cancers, which show significant tolerance to hypoxic insult." (PMID 28620317, 2017). "In this study, we identified a set of associated DEGs (CD44, CTGF, DPP4, CRYAB, EGLN3, FGF1, and FOS) with at least one functional enrichment, such as “angiogenesis”, “binding of endothelial cells”, “development of blood vessel”, MAPK signaling, HCM, and pathways in cancer." (PMID 28623314, 2017). "We found positive LASSO coefficients for the genes CDKN2A, EGLN3, KIF14, and RECQL4 that were upregulated in cancer compared with normal samples." (PMID 36552262, 2022). "Among the 10 top-ranked compounds for ELGN3, including Fe as a ligand, eight compounds targeted cancer genes and two out of the eight targeted EGLN1, which is paralog of EGLN3." (PMID 24565165, 2014).
cancer (continued). "Cytoplasmic P4Hs that hydroxylate HIF-1α, a master transcriptional regulator of cellular responses to hypoxia and well-established mediator of cancer progression, have also been identified (prolyl hydroxylase domain enzymes; PHD1/EGLN2, PHD2/EGLN1, and PHD3/EGLN3)." (PMID 35804902, 2022). "Literature review found that circ_SAR1A, circ-EGLN3 and circ_001842 could promote the progression of RCC, while circ_AKT3 and circ_RPL23A exhibited the low expression in RCC and played important roles in cancer suppression." (PMID 36578555, 2022). "Among the set of genes that we identify as being related to RCC, some were known from previous studies (e.g. ATP6V1B1, EGLN3, SLC25A5, TUBB, ALDOA); others had never before been associated with RCC, but have been identified with other cancers (e.g. ABL2, JAZF1, TFAP2A)." (PMID 19455236, 2007). "Several other candidate genes were found to be undetectable in whole blood, while most of the genes that were detectable (EGLN3, CAV2, ESM1, TMEM45A, NOL3, FABP7) did not exhibit significant dysregulation in expression between cancer and healthy PAXgene samples." (PMID 32013938, 2020).
infection (5 papers, 2013 to 2025). The state of being infected such as from the introduction of a foreign agent such as serum, vaccine, antigenic substance or organism. "However, the expression of Bax was significantly increased after NH4Cl exposure, which was rescued by infection of EGLN3-shRNA lentivirus." (PMID 35425766, 2022).
cardiac diseases (2 papers, 2019 to 2020). "Among them, some have been already reported to be involved in cardiac diseases, such as CORIN and EGLN3." (PMID 31902369, 2020).
benign tumors (1 paper, 2021). "We also assessed the linear variant of EGLN3 and found differential expression between patients with benign tumors compared to ccRCC patients." (PMID 35174071, 2021). "We observed increased linear EGLN3 expression in urine from patients with benign tumors (relative to healthy controls) compared to ccRCC patients." (PMID 35174071, 2021).
EGLN3 also shares sentences with these, for which no sentence is quoted: myocardial infarction (6 papers); colitis (5); colon carcinoma (5); anemia (4); melanoma (4); osteosarcoma (4); Sepsis (4); acute myeloid leukemia (3); ischemia (3); non-small cell lung carcinoma (3); pancreatic ductal adenocarcinoma (3); pancreatic endocrine tumors (3); type 2 diabetes (3); ampullary adenocarcinoma (2); astrocytoma (2); atherosclerosis (2); chronic kidney disease (2); colon adenocarcinoma (2); dyslipidemia (2); fibrosis (2); head and neck squamous cell carcinoma (2); hypercholesterolaemia (2); Hyperglycemia (2); inflammation (2); pancreatic adenocarcinoma (2); preeclampsia (2); squamous cell carcinoma (2); abscess (1); acute kidney injury (1); allergic disease (1).
A further 57 diseases each share a sentence with EGLN3 in 1 paper.